ALB (albumin)
Diseases named in the same sentence as ALB in open-access papers (continued):
Sharing a sentence is not in itself a finding about the gene and the disease.
Stroke (continued). "Multivariable linear regression demonstrated that stroke volume had an independent positive relationship with serum albumin, and an independent negative relationship with serum bilirubin." (PMID 38314569, 2024). "Based on these considerations, GPS can be used to predict stroke in endocarditis only if all different causes of CRP elevation and albumin reduction have been ruled out." (PMID 39292095, 2024). "Univariate logistic regression analysis showed significant differences in age (OR 1.044, 95% CI 1.017–1.072, p = 0.001), previous stroke (OR 3.289, 95% CI 1.296–8.344, p = 0.012), CRP (OR 0.990, 95% CI 0.986–0.995, p < 0.001), albumin (OR 1.559, 95% CI 1.017–2.390, p = 0.042)." (PMID 39734631, 2024). "The relationship between serum albumin and severe impairment of ADLs in stroke patients showed an L-shaped curve (non-linear, p = 0.002), with an inflection point at 38.0 g/L." (PMID 39835151, 2024). "Univariable Cox analysis showed that age, history of stroke, RDW, lower albumin, AST, CEA, CA19‐9, ΔRDW, ASA, the type of operation, TNM stage, pathological type, differentiation, postoperative adjuvant chemotherapy and neutrophil count were prognostic factors of CRC patients (all p < 0.05)." (PMID 37143237, 2023). "The concentration of serum BNDF, NE, ET and glutamate, and peripheral blood SOD, ALB, HB and CAT may suggest the function improvement of stroke patients." (PMID 37731856, 2023). "The remaining 17,303 participants were included in the research after those under 40, those without serum albumin levels and those without stroke data were phased out." (PMID 37682189, 2023). "Data from Western populations showed that, for every 0.4-mg/mmol increase in the urine albumin-to-creatinine ratio (UACR), the risk of a composite of CV events (i.e., MI, stroke, or CV mortality) increased by 5.9%, regardless of the diagnosis of T2DM." (PMID 37240509, 2023). "In a prospective followup of 60 months in Japanese adults under 75 years of age, moderately higher albuminuria assessed by the urine albumin-to-creatinine ratio (UACR) was an independent predictor of CV events, including stroke, myocardial infarction (MI), revascularization, and CV death." (PMID 37817566, 2023). "The meta-analysis of studies on biomarker changes after stroke rehabilitation revealed that rehabilitation can significantly increase the concentration of serum BDNF and NE, and peripheral blood SOD, ALB and HB, and CAT, and decrease the biomarkers of serum ET, glutamate, and TNF-α." (PMID 37731856, 2023). "The C-reactive protein-to-albumin ratio (CAR) is a new index that reflects the overall inflammatory status of patients with major diseases; however, no studies have reported the relationship between CAR and young stroke." (PMID 36457873, 2022). "ALB is the most abundant antioxidant in whole blood carrying nitric oxide, bilirubin, etc., which can prevent venous thrombosis and reduce the occurrence of PFO-related stroke." (PMID 35756923, 2022). "In univariate analysis, age, stroke history, AF, CHD, admission NIHSS score, discharge NIHSS score, admission mRS score, discharge mRS score, SPI-IIscore, ALB, CK, LDH, DD, Fib, WBC, Neutrophil, Monocyte, Hgb, RDW, and ESR were significantly associated with poor prognosis (p < 0.05)." (PMID 36206280, 2022). "Stroke patients had lower levels of serum transferrin, pre-albumin, and albumin compared to HR subjects, and in turn were lower in stroke patients with OD vs. patients without OD." (PMID 36703642, 2022). "A study in northern Manhattan followed 2,986 individuals without stroke for 12 years and found that a lower serum ALB level was a predictor of cryptogenic stroke incidence after adjustment for cardiovascular risk factors, body mass index, and inflammation." (PMID 35756923, 2022).
Stroke (continued). "Fasted blood concentrations of vitamins B1, B2, B6, A, D, and E, selenium, choline, CoQ10, albumin, pre-albumin, transferrin, DHA, EPA, LA, and ALA were all significantly lower in stroke compared to age- and sex-matched matched HR subjects, irrespective of OD status." (PMID 36703642, 2022). "Moreover, FC in stroke patients was positively correlated with CRP and negatively correlated with lymphocyte count and albumin." (PMID 35011900, 2021). "The fibrinogen-to-albumin ratio (FAR) which combines coagulation with nutritional status, is a new vital inflammatory biomarker for a variety of diseases, such as cervical cancer, oligodendroglial gliomas, acute coronary syndrome, and stroke." (PMID 35095715, 2021). "The associations between stroke outcomes and albumin, hemoglobin, and WBC have been reported, but Aspirin prescription has not been shown as beneficial to stroke outcomes as found in our current population study." (PMID 35356047, 2021). "Albumin expression within the ischemic areas was not significantly different between stroke models at any timepoint (1, 3, and 7 d post stroke)." (PMID 32492968, 2020). "In this study, we aimed to compare immediate postoperative results (e.g., drainage, erythrocyte transfusion, postoperative stroke, and mortality) in patients receiving heparin-albumin-coated and non-coated circuits." (PMID 33306317, 2020). "For instance, the albumin/globulin ratio was negatively correlated with total protein in healthy individual, however this was not significant in the stroke group." (PMID 32071823, 2020). "Nutritional assessment of stroke survivors: the nutrition assessment included two anthropometric measurements (MUAC and BMI), three biochemical indicators (uric acid, serum albumin, total protein) and the two haematological indices (total lymphocyte count, haemoglobin)." (PMID 33598073, 2020). "In conclusion, 3 weeks of supplementation with ALA did not have any significant effects on serum albumin, and oxidative stress and inflammatory biomarkers compared to control group in stroke patients." (PMID 32373498, 2020). "In multivariate Cox proportional hazards regression, patients with a glycemic gap >43 mg/dL presented a 7.22-fold greater risk of in-hospital mortality than those with a gap ≤43 mg/dL after adjusting for age, sex, prior stroke and levels of log BNP, AST and albumin." (PMID 31000758, 2019). "Albumin extravasation as a result of BBB leakage was assessed by planimetry in sham-stimulated rats and in rats undergoing MLR-HFS for 24 h, beginning 3 h after induction of photothrombotic stroke." (PMID 31430854, 2019). "Multivariate analysis showing the best amino acid positive and negative predictors of albumin and respectively haemoglobin in the stroke patients." (PMID 31412042, 2019). "This intramural albumin staining decreased further away from the infarct core, but was constantly more frequent in the vessels of the TGN-020-treated animals, especially in the acute phase of the stroke." (PMID 29295526, 2017). "However, there have been no studies performed examining pregnant women, smoking and albumin levels in connection with risk of stroke and coronary heart disease; therefore, we can only suspect that improper albumin concentrations may be a predictor of negative pregnancy outcomes." (PMID 27548057, 2016). "The adjusted hazard ratio (HR) per two-fold higher CRP concentration for all deaths was 1.29 (1.10-1.52), and after excluding PD-unrelated deaths, such as cancer or stroke, HR was 1.23 (1.01-1.49) (adjusted for age, sex, PD duration, modified Hohen-Yahr stages, MMSE scores, and serum albumin)." (PMID 26218286, 2015). "Age, gender, social problems, education, body mass index (BMI), comorbidities, history of stroke, use vitamin K antagonists, inadequate fatty fish intake, serum thyroid-stimulating hormone (TSH), vitamin B12, albumin, and estimated glomerular filtration rate were used as confounders." (PMID 26274973, 2015).
Stroke (continued). "Moreover, 2 h after tMCAO leaks in the BBB were found even for bigger molecules such as Evans Blue-albumin complexes (>60,000 Da) indicating a rapid opening of the BBB after stroke." (PMID 25389390, 2014). "Serum albumin of stroke patients above 65 years was not significantly different from those below 65 years as shown in." (PMID 23565300, 2013). "Our results indicate that inhibiting HIF-1 by YC-1 reduces the permeability to albumin, but it does not change the permeability to water and cannot inhibit the formation of brain edema after stroke." (PMID 22110762, 2011). "Further adjustment for smoking, blood pressure, body mass index, serum albumin, myocardial infarction or stroke did not materially influence the study results in HD and PD patients." (PMID 22182634, 2011). "There were also significant correlations between urine albumin and cardiovascular disease and angina but not with death due to myocardial infarction, heart failure or stroke." (PMID 19609391, 2008). "According to our knowledge, this is the first study with a relatively large samples size to focus on the prognostic value of diverse albumin-based malnutritional markers among the hyper-acute stage stroke patients no matter they undergoing IVT/EVT alone or EVT bridged with IVT." (PMID 40832639, 2025). "Prognostic nutritional index (PNI) (calculated as serum albumin (g/dL) level × 10) + (lymphocyte (103/uL) × 0.005) is used to obtain prognostic information in patients with malignancy, heart failure, peripheral artery disease (PAD), stroke and coronary artery disease." (PMID 39555199, 2024). "DKD patients were mostly older, male, and had higher levels of RDW, RA, UA, fasting glucose, HbA1c, creatinine, and higher instances of CHD and stroke, but lower level of eGFR, albumin, as compared with those without DKD (p < 0.05) both in the NHANES and the WMU cohorts." (PMID 38923843, 2024). "Additionally, further large scales studies are required to confirm findings suggestive of a non-linear relationship between albumin and post-stroke outcomes." (PMID 38794724, 2024). "Currently, the indicators that can be used to predict the prognosis of stroke patients include National Institutes of Health Stroke Scale (NIHSS), Red Blood Cell Distribution Width (RDW), Prognostic Nutritional Index (PNI), and Hemoglobin, Albumin, Lymphocyte, and Platelet score (HALP)." (PMID 39044281, 2024). "Second, evaluating serum albumin concentrations concerning the subtype and degree of stroke is constrained because individuals with stroke could not provide precise information about their stroke." (PMID 37682189, 2023). "The ROCKET (Rivaroxaban Once‐daily oral direct factor Xa inhibition Compared with vitamin K antagonism for prevention of stroke and Embolism Trial) trial also identified reduced serum albumin and platelet count, two parameters that were not available for patients in this study." (PMID 37596725, 2023). "First, serum albumin and globulin levels were not tested immediately after stroke." (PMID 36794538, 2023). "However, studies of ITE in stroke patients are scarce and, to our best knowledge, there is no such discussion of warfarin and human albumin, which are common drugs." (PMID 36816575, 2023). "Notably, several studies on elderly patients with stroke or acute coronary syndrome observed low serum concentration of albumin is a negative prognostic index for in-hospital mortality." (PMID 37957767, 2023). "By logistic regression analysis, we found that plasma albumin levels could not predict the risks of in-hospital or 6 months stroke." (PMID 36186979, 2022). "The use of endogenous albumin to measure BBB permeability may alleviate the concerns of some investigators regarding the use of exogenous BBB tracers, including EBD, in preclinical stroke studies." (PMID 36224001, 2022). "The negative coefficients of albumin and hemoglobin found in our study indicated higher values might improve stroke outcomes." (PMID 35356047, 2021).
Stroke (continued). "Fourth, urine albumin was not measured in this study and we have previously shown that the relationship between albuminuria and stroke may be mechanistically different to that of low eGFR and stroke." (PMID 32883874, 2021). "Compared with patients without prior stroke, patients with a positive history had significant leukocytosis, increased neutrophils, lymphopenia, prothrombin time and D-dimer, lower platelet count, hemoglobin, albumin, and alanine aminotransferase." (PMID 35265632, 2021). "Noteworthy, the detection of FITC-albumin loaded endothelial vesicles and caveolae in cells showing an endothelial edema at early time points after ischemia induction further substantiates the concept in favor of a transcellular mechanism of BBB breakdown in the setting of stroke." (PMID 30744693, 2019). "There was no albumin infiltration in the non-stroke brains (n = 4)." (PMID 31708728, 2019). "Albumin was the strongest negative correlate for stroke in our results." (PMID 27439507, 2016). "To demonstrate this, we returned to the same sample set from the previous study and applied immunoenrichment coupled to mass spectrometry to capture and quantify albumin-bound proteins at baseline and 3–12 month follow up after stroke–related PFO, with and without endovascular closure." (PMID 25678897, 2015). "Also, serum albumin measured within 24 h of stroke onset may not be affected by the acute stress response after stroke due to the long half-life of albumin." (PMID 37686771, 2023). "Though serum albumin may not be of clinical significance, low levels could indicate the need for a complete and detailed nutritional assessment and potentially be a link to poorer outcomes in individuals who have suffered stroke." (PMID 35640017, 2022). "In addition, another limitation is that the uric acid and albumin to globulin ratio could not be obtained before intravenous thrombolysis in some stroke centers, which may limit the application of the nomogram before intravenous thrombolysis in these centers." (PMID 36158944, 2022). "Although BBB permeability profiles for ions and dextrans of smaller molecular weight may not necessarily comply with the applied FITC-albumin, the latter is also of clinical interest as the extravasation of albumin is known to promote epileptic seizures as a typical complication of stroke." (PMID 30744693, 2019). "Notably, albumin accumulation at 24 h did not significantly differ between rt-PA and vehicle in both 0.5 and 4 h stroke periods, indicating that a similar degree of BBB permeation to plasma proteins developed with or without the thrombolytic (see “Discussion”)." (PMID 29157263, 2017). "Thus, the histological albumin and H&E measurements provide evidence to support MRI results, which demonstrated that BMSC treatment significantly reduced BBB disruption and leads to reduced hemorrhage after stroke in T2DM rats, compared with the vehicle treated T2DM rats." (PMID 26900843, 2016). "Second, although fusion of Infestin-4 to human albumin dramatically improved the half-life of this protein in mice, i.e. from 0.3 to 4.6 hours, pharmacokinetic characteristics of this molecule may not be optimal for prophylactic regimes in stroke prevention." (PMID 26815580, 2016). "However, albumin at high dose expands intravascular volume and may precipitate congestive heart failure, but with concomitant NPD1 synthesis in the ipsilateral side after stroke." (PMID 23437099, 2013). "Patients with PICS were more likely to be older, have a more severe condition and stroke, and have lower albumin on day one and higher CRP and lower albumin and lymphocyte counts on day 14 than those with Non-PICS." (PMID 36233660, 2022). "This present study has rather shown that though 88.7% of the stroke survivors were malnourished, it was not due to PEM, as a relatively high proportion of the participants had normal levels of albumin and total protein." (PMID 33598073, 2020).
Stroke (continued). "Across the overall population, stroke volume had a weak negative correlation with serum urea, bilirubin, aspartate aminotransferase, ALP, γ‐glutamyl transferase, CRP, and troponin‐T, and a weak positive correlation with serum albumin." (PMID 38314569, 2024). "However, the albumin level was affected with nutritional status in the present study and malnourished stroke patients in the last quartile of PG-SGA experienced low and non-significant level of albumin compared to second quartile." (PMID 34847871, 2021). "Patients in group A had a significantly higher incidence of congestive heart failure (CHF), cerebrovascular accident (CVA), dialysis, CLTI, and nonambulatory status than those in group B. BMI, serum albumin level, cholesterol level, and GNRI were significantly higher in group B patients." (PMID 33177036, 2020). "Baseline serum albumin levels were not correlated with mean S100BB serum levels (r = 0.16, p > 0.05) or the patients’ neurological state (correlation with NIHSS on day 10 of stroke: r = 0.12, p > 0.05)." (PMID 26757706, 2016). "NT-proBNP, albumin, and globulin are useful for early diagnosis of CES; the increase of NT-proBNP over 200 pg/mL, G/A ratio > 0.7, with or without AF and in presence of severe stroke, supports the suspicion of cardioembolism." (PMID 24734185, 2014). "The increased accumulation of exosomes at the site of stroke following LIPFUS was probably due to transient increased BBB opening in stroke areas or transient inflammation and increased expression of adhesion molecules as we have not detected extravascular albumin in the brain parenchyma." (PMID 40271117, 2025). "The data show that combination BMSC and Niaspan treatment of stroke in T1DM initiated at 24h after MCAo did not decrease brain hemorrhage transformation, but decreased BBB leakage compared with BMSC monotherapy in T1DM animals identified by albumin staining (p<0.05)." (PMID 24303036, 2013). "Finally, we showed that, in addition to exogenous tracers, endogenous albumin, to which EBD normally binds, is a circulating protein that is extravasated into the ipsilateral ischemic hemisphere but not the nonischemic hemisphere in our preclinical stroke model." (PMID 36224001, 2022).